MMP16 (matrix metallopeptidase 16)
Diseases named in the same sentence as MMP16 in open-access papers (continued):
Sharing a sentence is not in itself a finding about the gene and the disease.
colorectal cancer (7 papers, 2013 to 2024). A primary or metastatic malignant neoplasm that affects the colon or rectum. "Interestingly, additional common somatic mutations occurred in the SERPINE1 p.R210H, a hotspot in colorectal cancer, and MMP16 p.Y290H ECM remodelers." (PMID 33853673, 2021). "miRNAs, which are regulators of autophagy, have also been reported to regulate autophagy, for example, the effect of miRNA and autophagy on colorectal cancer; miRNA-192-5p attenuates airway remodeling and autophagy in asthma by targeting MMP-16 and ATG7." (PMID 36388165, 2022). "However, the contribution of MMP16 to colorectal cancer (CRC) remains elusive." (PMID 28422174, 2017). "Another study identified miR-328 in the SP of colorectal cancer cells and demonstrated that expression of miR-328 correlated with high a SP fraction, and that the main targets of miR-328 were the ABCG2 transporter and the MMP16 gene." (PMID 24386225, 2013).
prostate carcinoma (7 papers, 2013 to 2026). A carcinoma that arises from epithelial cells of the prostate gland. "Five SNP-SNP interactions in three gene pairs (MMP16+ ROBO1, MMP16+ CSF1, and MMP16+ EGFR) were identified to be associated with aggressive prostate cancer in both groups." (PMID 23593148, 2013). "The family of mammalian MMPs includes 24 members, but unlike MMP-1, -2 and -9, the role of MMP16 in prostate cancer has not been well investigated." (PMID 23593148, 2013). "With the MMP16 and EGFR, men with the genotype combination of GA/AA and AA in a SNP pair of rs1401862 and rs6964705 tended to be less likely (OR = 0.58, p-value = 0.011) have aggressive prostate cancer than other genotype combinations of the SNP pairs in the CGEMS group." (PMID 23593148, 2013).
pancreatic cancer (6 papers, 2013 to 2025). "MMP16 has been shown to be associated with pancreatic cancer cell migration and invasion and lung development." (PMID 23593148, 2013). "has-miR-546b-5p had inhibitory effect on pancreatic cancer cell migration and invasion by targeting MMP16." (PMID 24982669, 2014). "Previous in vitro analyses showed that miR-155 inhibited cell migration of human cardiomyocyte progenitor cells via targeting of MMP-16 and, in pancreatic cancer cell, miR-155 plays an important role in the regulation of cell migration by modulating the STAT3 signaling pathway." (PMID 29161332, 2017).
asthma (5 papers, 2021 to 2025). "Its overexpression was associated with decreased levels of ovalbumin-specific IgE, IL-4, IL-5, and IL-13, contributing to improved asthma outcomes by limiting airway remodeling and autophagy through the downregulation of matrix metalloproteinase (MMP)-16 and autophagy related 7 (ATG7)." (PMID 40871238, 2025). "Moreover, Lou and coworkers demonstrated that the levels of miR-192-5p are decreased in asthmatic mice, and the overexpression of miR-192-5p alleviates airway remodeling and autophagy in asthma by targeting matrix metalloproteinase-16 (MMP-16) and autophagy-related 7 (ATG7) in vitro and in vivo." (PMID 33708127, 2021). "Using bioinformatics analysis, the target genes interacting with miRNAs related to the airway inflammatory response, airway remodeling and other pathological change processes in asthma were screened as ABL2, MMP16 and PDE7A." (PMID 36611831, 2022).
colon cancer (5 papers, 2015 to 2024). "MMP16 is up-regulated in several types of cancers, including breast, lung, prostate, and colon cancer." (PMID 38560573, 2024). "To determine the role of MMP16 in colon cancer cells viability and progression, we used lentivirus-mediated method to establishe stable MMP16-knockdown in LoVo and RKO cells, and the knockdown efficiency were v determined by RT-PCR and western blotting." (PMID 28422174, 2017). "Another potentially important target, MMP16, has been shown to be increased in stem like colon cancer cells." (PMID 26287603, 2015). "Functional study found that silencing MMP16 expression could inhibit migration and invasion of colon cancer cells." (PMID 28422174, 2017). "Furthermore, functional study found knockdown of MMP16 expression could inhibit the migration and invasion of colon cancer cells." (PMID 28422174, 2017).
ovarian carcinoma (5 papers, 2013 to 2025). A malignant neoplasm originating from the surface ovarian epithelium. "A prior study found that BBR increased miR-145 expression while decreasing MMP16 expression, reducing the proliferation, migration, and metastasis of ovarian cancer SKOV3 and 3AO cells." (PMID 39896297, 2025). "In conclusion, our data showed that berberine promoted miR-145 expression and decreased MMP16 expression, thus inhibiting proliferation, migration and metastasis of ovarian cancer SKOV3 and 3AO cells." (PMID 33407764, 2021). "In our study, we found berberine inhibited the expression of MMP16 and thus inhibited the proliferation, migration and metastasis of ovarian cancer cells." (PMID 33407764, 2021). "In addition, MMP2 and MMP16 transcripts, which are recognized proteins mediating enhanced migration and metastasis of ovarian carcinoma cells, were also reduced." (PMID 35562985, 2022). "In present study, we found berberine could increase miR-145 expression, and miR-145 targeted MMP16 directly, these results suggest that miR-145 may be a target of berberine in the treatment of ovarian cancer." (PMID 33407764, 2021). "In this study, we have discovered for the first time that berberine could promote the expression of miRNA-145, thus inhibiting the expression of MMP16 and the progression of ovarian cancer, promising a novel natural agent for anti-ovarian cancer therapy." (PMID 33407764, 2021). "Together, our results revealed that berberine inhibited proliferation, migration and invasion through miR-145/MMP16 in SKOV3 and 3AO cells, highlighting the potentiality of berberine to be used as a therapeutic agent for ovarian cancer." (PMID 33407764, 2021). "However, the mechanism of MMP16 in ovarian cancer remains unclear." (PMID 33407764, 2021).
renal carcinoma (5 papers, 2019 to 2023). A carcinoma arising from the epithelium of the renal parenchyma or the renal pelvis. "For example, by sponging miR-146b-5p, HOXA11-AS can upregulate MMP16 to accelerate the development and metastasis of renal cancer cells." (PMID 35368660, 2022). "HOXA11-AS could act as a ceRNA that repressed miR-146b-5p expression, regulating its downstream target MMP16 in renal cancer." (PMID 37059588, 2023). "miR-146b-5p may serve as an inhibitor role to suppress the aberrant proliferation and invasion of renal cancer cells via blocking the expression of MMP16, while few studies have revealed its role and functions in HCC." (PMID 35340237, 2022). "Moreover, HOXA11-AS could promote renal cancer cells growth and invasion by modulating the miR-146b-5p–MMP16 axis." (PMID 31319799, 2019).
Bladder cancer (4 papers, 2024 to 2025). "Moreover, MMP9, MMP12, MMP14, and MMP16-enriched KEGG pathways include “Bladder cancer, endocrine resistance, and relaxin signaling pathway” etc.." (PMID 39493455, 2024). "Moreover, MMP2, MMP9, MMP12, and MMP16-enriched KEGG pathways include “Bladder cancer, endocrine resistance, and relaxin signaling pathway”, etc.." (PMID 38560573, 2024). "The MMPs with the highest correlation with GHR expression in both female and male patients with bladder cancer were MMP2 (rho = 0.472 (F), 0.457 (M)), MMP16 (rho = 0.464 (F), 0.509 (M)), and MMP23B (rho = 0.316 (F), 0.452 (M))." (PMID 40806252, 2025).
dental caries (4 papers, 2017 to 2022). The decay of a tooth, in which it becomes softened, discolored, and/or porous. "Investigating the genetic association of MMP-10, MMP-14, and MMP-16 with dental caries shows that MMP-16 SNP rs2046315 is associated with dental caries." (PMID 36012195, 2022). "Only MMP16 SNPs (rs2046315 and rs10429371) were significantly associated with dental caries in an individual sample of Caucasian adults, and via meta-analysis across 8 adult samples after gene-wise adjustment for multiple comparisons." (PMID 32398053, 2020). "We investigated 28 SNPS in or near three MMP genes (MMP10, MMP14, and MMP16) for evidence of association with dental caries experience in 13 race- and age-stratified samples from 6 independent studies (n = 3600)." (PMID 28348596, 2017). "Here we investigated 28 genetic variants spanning the MMP10, MMP14, and MMP16 genes to detect association with dental caries experience in 13 age- and race-stratified (n = 3,587) samples from 6 parent studies." (PMID 28348596, 2017). "Significant evidence of association was seen between two SNPs upstream of MMP16 with dental caries." (PMID 29849633, 2018). "The aim of the study was to analyse Czech children with primary/permanent dentition polymorphisms in those genes encoding MMP2, MMP3, MMP9, MMP13, MMP16, and MMP20, which had been previously associated with dental caries in other populations." (PMID 32398053, 2020). "Although MMP16 is still a logical candidate to pursue, we did not strengthen evidence for its role in dental caries." (PMID 28348596, 2017).
allergic asthma (3 papers, 2022 to 2025). A asthma with a basis in a pathological type I hypersensitivity reaction. "Studies have shown higher expression of MMP16 in allergic asthma mice compared to normal mice, and regulating MMP16 expression can reduce fibrosis." (PMID 38871957, 2025).
aortic stenosis (2 papers, 2020 to 2022). Aortic valve stenosis is a aortic valve disease caused by the incomplete opening of the aortic valve. "A study evaluating atrial remodeling in aortic stenosis patients with chronic AF showed a decrease in the MMP16/TIMP4 ratio in patients with AF along with an increased serum TIMP1 and TIMP2 proteins." (PMID 36312240, 2022). "This is the first study that suggests MMP16/TIMP4 as a marker of disease, specifically, a marker of chronic AF in aortic stenosis patients." (PMID 33129260, 2020). "Atrial fibrillation patients with severe aortic stenosis present increased atrial fibrosis and collagen type III synthesis, with extracellular matrix remodelling demonstrated by a decrease in the MMP16/TIMP4 ratio, along with an increased serum TIMP1 and TIMP2 proteins." (PMID 33129260, 2020).
bronchopulmonary dysplasia (2 papers, 2008 to 2014). Bronchopulmonary dysplasia is a chronic respiratory disease that results from complications related to lung injury during the treatment of infant acute respiratory distress syndrome in low-birth-weight premature infants or from abnormal lung development in older infants. "In conclusion, we identify MMP16 as a possible new regulator of lung alveolar development and provide evidence that MMP16 polymorphisms are associated with protection from bronchopulmonary dysplasia in highly premature infants." (PMID 18784838, 2008).
cervical carcinoma (2 papers, 2012 to 2024). A carcinoma arising from either the exocervical squamous epithelium or the endocervical glandular epithelium. "A high expression of MMP16 mRNA was observed in all the tissues, though, the levels were significantly higher in the nasopharyngeal and cervical cancers than the normal tissues (p < 0.05)." (PMID 39073693, 2024). "The current study reports for the first time a comparative analysis of the expression pattern of AKT, IQGAP1, and MMP16 in HPV‐associated nasopharyngeal and cervical cancers." (PMID 39073693, 2024). "Interestingly, in a previous study no expression of MMP-12 or MMP-16 was found in HPV harboring cervical carcinoma cell lines." (PMID 22863036, 2012).
cleft palate (2 papers, 2010 to 2019). Cleft palate is a fissure type embryopathy that affects the soft and hard palate to varying degrees. "Interestingly, combined double knockout of Mmp14 and Mmp16 in mice leads to severe structural and craniofacial defects, including severe dysfunction in palatal shelf formation and cleft palate in 80% of the embryos." (PMID 31921852, 2019). "While MMP and TIMP expressions appear to be critical throughout all stages of palatal development, knockout mice for Timp1, Timp2, Timp3, Timp4, Mmp2, Mmp9, Mmp13, Mmp14, Mmp16, and Mmp25 do not develop cleft palate." (PMID 31921852, 2019).
cutaneous melanoma (2 papers, 2016 to 2023). A primary melanoma arising from atypical melanocytes in the skin. "In general, the expression of MMP2, MMP13, MMP16, MMP17 and MMP25 were significantly associated with skin cutaneous melanoma (SKCM) patients prognosis, among which MMP2 low expression benefited patients the most." (PMID 36788565, 2023). "For example, increased MMP16 expression mediated a proteolytic switch to facilitate metastasis, and lymphatic invasion and predicted aggressive progression in cutaneous melanoma." (PMID 27340864, 2016).
glioblastoma (2 papers, 2020 to 2021). The most malignant astrocytic tumor (WHO grade IV). "Of these, PAI-1/SERPINE1 and MMP16 showed pathogenic mutations in the FGFR2 tumors, a novel finding in glioblastoma." (PMID 33853673, 2021).
Hyperglycemia (2 papers, 2018). An increased concentration of glucose in the blood. "MMP16 was selected to be validated by qRT-PCR showing that hyperglycemia increased the mRNA level (1.4-fold, p = 0.023) compared to control." (PMID 29351188, 2018). "There was a decrease in MMP16 expression under hyperglycemia-CoCl2 at 12 h of CoCl2 (−1.9-fold, p < 0.001) compared to hyperglycemia alone." (PMID 29351188, 2018). "Therefore, metformin’s dual effect in hyperglycemia-chemical hypoxia is mediated by direct effect on VEGFR1/R2 leading to activation of cell migration through MMP16 and ROCK1 upregulation, and inhibition of apoptosis by increase in phospho-ERK1/2 and FABP4, components of VEGF signaling cascades." (PMID 29351188, 2018). "Our microarray experiments demonstrated that metformin upregulated downstream targets in VEGFA pathway; MMP16, FABP4, ROCK1, TFPI2, CXCL-8, and LY96 under hyperglycemia-CoCl2, which play a part in cell migration." (PMID 29351188, 2018). "However, metformin significantly increased the mRNA level of MMP16 by 1.5-fold, p = 0.04 under hyperglycemia-CoCl2 at 12 h of CoCl2 versus parallel conditions without metformin." (PMID 29351188, 2018).
liver cancer (2 papers, 2017 to 2021). An epithelial or non-epithelial malignant neoplasm that arises from the liver. "Inhibition of MMP16 expression in HCC represents an attractive target in liver cancer therapy." (PMID 29069779, 2017).
lymph node metastasis (2 papers, 2024 to 2025). "MMP16 expression was positively correlated with lymph node metastasis (p = 0.0012) and increased risk of tumor recurrence (p = 0.0003)." (PMID 40869275, 2025). "MMP16 expression varied with age, tumor size, histology, clinical stage, lymph node metastasis, and PR status." (PMID 39267845, 2024).
migraine (2 papers, 2014 to 2021). "Of note, a polymorphic expression of PRDM16 has been, together with MMP16, also linked to modulated therapy success with anticonvulsants in migraine." (PMID 35222013, 2021). "Furthermore, genetic variants related to MMP16, TGFBR2, TSPAN2, and LMP1 have been linked to therapy outcome changes with sartans in migraine." (PMID 35222013, 2021). "With the AIC penalty, five additional SNPs were assigned “non-null” models and only one, rs10504861 (near MMP16), displayed preferential association suggesting stronger association with active migraine." (PMID 24852292, 2014). "Only rs10504861 (near MMP16) in the previous analysis was identified exclusively in a previous sub-analysis restricted to MO and therefore including only the 1,826 WGHS MO cases rather than the 5,122 cases with history of any migraine." (PMID 24852292, 2014). "Second, some SNPs show no selectivity (i.e. “basic” model) for migraine attack frequency ≥6/year but selectivity (i.e. “subset” or “inverse subset” models) for other characteristics, for example aura status (rs11172113 [LRP1], rs6478241 [ASTN2], rs13208321 [FLH5], rs10504861 [near MMP16])." (PMID 24852292, 2014).
acute myeloid leukemia (1 paper, 2021). Acute myeloid leukemia (AML) is a group of neoplasms arising from precursor cells committed to the myeloid cell-line differentiation. "The obtained results show that the expression of MMP2 and MMP16 genes is reduced while the expression of MMP9 is unchanged in patients with acute myeloid leukemia." (PMID 34035811, 2021). "In the present study, changes in mRNA expression levels of selected metalloproteinase genes (MMP2, MMP9, and MMP16) in acute myeloid leukemia were evaluated." (PMID 34035811, 2021). "The expression level of the MMP2, MMP9, and MMP16 genes does not depend on the presence of cytogenetic changes in cancer cells and gender and age of patients with acute myeloid leukemia." (PMID 34035811, 2021). "The cells of people with acute myeloid leukemia have a lower relative gene expression level of the MMP2 and MMP16 but no MMP9 compared to patients without cancer." (PMID 34035811, 2021).
adenomyosis (1 paper, 2022). The growth of endometrial tissue inside the muscular wall of the uterine corpus. "We analyzed MT2-MMP (MMP15) and MT3-MMP (MMP16) in eutopic endometrium with and without endometriosis and with and without adenomyosis and ectopic endometrium of deep infiltrating endometriosis (DIE), peritoneal endometriosis (PE), and ovarian endometriosis (Ov) by immunohistochemistry." (PMID 35453827, 2022).
Arthritis (1 paper, 2006). Inflammation of a joint. "IL-1 and/or OSM also failed to clearly modulate MMP-16 expression in a human chondrocyte cell line, and a role of MMP-16 in arthritis remains unclear although it is expressed in rheumatoid synovium and is elevated in end-stage OA compared with normal cartilage." (PMID 16919164, 2006).
cervical dysplasia (1 paper, 2012). "In the present study we found increasing staining for MMP-16 along with the development of cervical dysplasia, in agreement with a number of previous studies, whereas MMP-7 expression remained virtually similar." (PMID 22863036, 2012).
chordoma (1 paper, 2021). Chordomas are rare malignant tumors arising from embryonic remnants of the notochord in axial skeleton. "Some studies have indicated that high expression of MMP16 is associated with the proliferation, migration, and invasion of cutaneous squamous cell carcinoma cells, while knockdown of MMP16 could inhibit cell proliferation and invasion in chordoma cells." (PMID 34587931, 2021).
Cirrhosis (1 paper, 2023). A chronic disorder of the liver in which liver tissue becomes scarred and is partially replaced by regenerative nodules and fibrotic tissue resulting in loss of liver function. "Most liver cells have high levels of MMP-2, -3, -7, and -16 during viral hepatitis and HCC; MMP-8, -9, -10-, -12, -13, -14, and MMP-16 during HCC and cirrhosis; and MMP-24 during liver regeneration." (PMID 37509493, 2023).
colon adenocarcinoma (1 paper, 2016). "To determine the effect of MMP16 on tumorigenesis and progression of colon adenocarcinoma cells, we used lentivirus-mediated silencing GC cell lines, AGS and MGC-803, and the knockdown efficient of the MMP16 was determined by RT-PCR and western blotting." (PMID 27340864, 2016).
cystic fibrosis (1 paper, 2023). Autosomal recessive disorder caused by pathogenic variants in the CFTR gene (cystic fibrosis transmembrane conductance regulator), which encodes a chloride and bicarbonate channel expressed in epithelial cells, and follow the diagnosis criteria. "Notably, using a quantitative proteomic and bioinformatic approach, we identified several metalloprotease proteins usually involved in cystic fibrosis, such as matrix metalloproteinase 8 (MMP8), MMP9, and matrix metalloproteinase 16 (MMP16)." (PMID 37686190, 2023).
diffuse astrocytoma (1 paper, 2025). A low-grade (WHO grade II) astrocytic neoplasm. "“MYB- or MYBL1-altered diffuse astrocytoma” is a rare entity defined by a canonical fusion event of MYB- or MYB1L, with the most common partner genes PCDHGA1, MMP16, and MAML2." (PMID 40392954, 2025).